CRHBP (corticotropin releasing hormone binding protein)
Diseases named in the same sentence as CRHBP in open-access papers (continued):
Sharing a sentence is not in itself a finding about the gene and the disease.
tumor (8 papers, 2013 to 2025). "CRHBP expression is significantly low in the majority of tumor types and is associated with survival prognosis, ICP markers, TMB, and microsatellite instability (MSI)." (PMID 38326407, 2024). "Our statistical evaluation of CRHBP mRNA levels within the tumor group revealed that reduced CRHBP levels are associated with advanced, metastasized and higher stages of disease (p<0.001, p=0.026, p=0.028 respectively)." (PMID 23607589, 2013). "Similarly, the expression of CRHBP has been recently shown to be negatively associated with the tumor size in HCC." (PMID 31277598, 2019). "To answer whether high CGI-methylation of CRHBP associates with tumor tissues and decreased CRHBP expression in RCC, we investigated paired normal and tumoral tissue samples from 66 nephrectomy specimens by the use of qMSP." (PMID 27695045, 2016). "Moreover, in silico validation by use of the KIRC dataset provided by TCGA network study confirmed tumor specific hypermethylation of CRHBP, epigenetic silencing of CRHBP mRNA expression and association of CRHBP methylation with biological aggressive tumor characteristics." (PMID 27695045, 2016). "CRHBP has a significant impact on tumor immunity, treatment, and prognosis, and has the potential as a cancer treatment target and prognostic indicator." (PMID 38326407, 2024). "We used univariate Cox regression analysis in the LIHC cohort of TCGA database to evaluate the prognostic significance of common clinical characteristics (age, gender, tumor grade, stage) and CRHBP expression level." (PMID 38326407, 2024). "The results showed that only tumor stage and CRHBP expression level had independent prognostic value." (PMID 38326407, 2024). "To further verify the effect of CRHBP on tumor cell biology in LIHC, we used cellular and molecular biological techniques." (PMID 38326407, 2024). "We analyzed the levels of CRHBP expression in 20 tumor and normal tissues utilizing TCGA database, and we carried out a similar study for 27 tumor types using the combined TCGA and GTEx datasets." (PMID 38326407, 2024). "After adjusting for age, gender and tumor grade, multivariate Cox regression analysis showed that tumor stage and CRHBP expression were still independent prognostic factors for LIHC." (PMID 38326407, 2024). "The results showed that both mRNA and protein expression of CRHBP in tumor tissues were significantly downregulated compared with adjacent non-tumor tissues." (PMID 31570754, 2020). "Consistently, the data of tumor xenograft model indicated that overexpression of CRHBP inhibited tumor growth and metastasis in mice." (PMID 31570754, 2020). "We discovered that CRHBP overexpression resulted in a significant reduction in tumor volume and weight compared with the control group tumors." (PMID 31570754, 2020). "Then, ccRCC patients with a decreased expression of CRHBP in tumor tissues had significantly poor survival by TCGA ccRCC datasets and verified by clinical samples as well as RCC cell lines." (PMID 31570754, 2020). "Relative methylation of the CRHBP CpG island (CGI) was determined in 17 tumor cell lines as well as 86 ccRCC samples and 66 paired normal tissues using pyrosequencing and quantitative methylation specific PCR of bisulfite converted DNA." (PMID 27695045, 2016).
tumor (continued). "Assessment of median methylation levels for normal and tumor tissues revealed a difference of 4.37 natural logarithmic units corresponding to an approx. 80 fold increase in highly methylated CRHBP CGI sequences in the tumor group." (PMID 27695045, 2016). "Next we used immunofluorescence analysis of a tissue microarray representing 17 cc-RCC to characterize the distribution of immunopositivity of CRHBP in normal and tumor tissues." (PMID 23607589, 2013). "Therefore, we also used cellular and molecular biological methods to explore the impact of CRHBP on the basic tumor phenotype and function of LIHC." (PMID 38326407, 2024). "CRHBP has a tumor suppressor function in LIHC, according to cell and molecular biology trials." (PMID 38326407, 2024). "The SPARCL1+ and CRHBP+ were identified for tumor and normal derivation respectively." (PMID 35017463, 2022). "We explored the influences of CRHBP on tumor cell migration and invasion." (PMID 31570754, 2020). "Analysis of paired normal and tumor tissue samples demonstrated that more than half of the tumor tissues exhibited a substantial increase in methylation thus showing a clear overall hypermethylation of the CRHBP–CGI in RCC tumors (p<1*10−12, paired t-test)." (PMID 27695045, 2016). "In view of our previous findings, demonstrating that mRNA-expression of the CRHBP gene is depleted in tumor tissues, we hypothesized that CRHBP may be epigenetically silenced thus representing a new target of DNA hypermethylation in ccRCC." (PMID 27695045, 2016). "Conclusively, our analysis clearly demonstrated epigenetic silencing of CRHBP hence showing for the first time that a member of the CRH-system is epigenetically silenced in tumor cells and thus providing strong evidence for an involvement of CRH members in human tumorigenesis." (PMID 27695045, 2016). "Therefore functional analyses such as targeted knock out of CRHBP gene in a cc-RCC tumor model or epigenetic characterization of the UCN system should provide an improved understanding of the CRHBP contribution to the pathogenesis of cc-RCC." (PMID 23607589, 2013). "In contrast to the detection of CRHBP immunopositivity, mRNA levels in tumor tissue could be differentiated." (PMID 23607589, 2013). "However, it is still unclear what role CRHBP has in tumor immunity and prognosis prediction." (PMID 38326407, 2024). "Using databases such as the Cancer Genome Atlas (TCGA), Gene Expression Omnibus (GEO), Tumor Protein Database, Timer Database, and Gene Expression Profiling Interactive Analysis (GEPIA), we evaluated the potential role of CRHBP in diverse cancers." (PMID 38326407, 2024).
cancer (6 papers, 2013 to 2024). A tumor composed of atypical neoplastic, often pleomorphic cells that invade other tissues. "Our studies illustrate that the expression variations and prognostic importance of CRHBP need further investigation in more cancer types." (PMID 38326407, 2024). "In this context, based on the special significance of CRHBP in various tumors, it is necessary for us to conduct a pan-cancer analysis, which is the first time." (PMID 38326407, 2024). "As for these, the number of previous studies on CRHBP in cancer is limited, and only a few results are generally consistent with our findings." (PMID 38326407, 2024). "We evaluated the connection of CRHBP expression with several immune checkpoint markers in various cancer types to further explore the potential of CRHBP in immunotherapy." (PMID 38326407, 2024). "CRHBP expression level also shown significant statistical difference between different pathological stages in the whole pan-cancer." (PMID 38326407, 2024). "We discovered that the expression levels of the majority of immunological checkpoint markers in various cancers were favorably connected with the expression levels of CRHBP, while just a few were negatively correlated." (PMID 38326407, 2024). "Our results suggest that CRHBP is involved in the development of many different forms of cancer and has potential as a pan-cancer biomarker that may predict survival prognosis." (PMID 38326407, 2024). "We may infer from the data above that the immunological and molecular subtypes of pan-cancer express CRHBP differently." (PMID 38326407, 2024). "In sum, we could speculate that CRHBP can be used as a pan-cancer biomarker to predict immunotherapy success, and perhaps as an additional target for enhancing ICP gene immunotherapy." (PMID 38326407, 2024). "The results of GSE68417, GSE36895, GSE53757 and GSE66270 datasets showed significantly lower CRHBP expression in ccRCC group than those in the adjacent non-cancer group, revealing that CRHBP could serve as biomarker for ccRCC prognosis and diagnosis." (PMID 31570754, 2020). "Besides CLS-439 all cancer cell lines analysed exhibited a degree of relative methylation >50% suggesting CRHBP CGI methylation as a frequent event in urological tumor models." (PMID 27695045, 2016). "Considering that ligand concentrations of locally required peptides have been shown to affect proliferation and angiogenesis of cancer cells, we suppose that the reduction of CRHBP mRNA and protein expression in tumors also contribute in those pivotal tumorigenic processes." (PMID 23607589, 2013). "In conclusion, we performed the first investigation of CRHBP in pan-cancer, and the findings revealed that CRHBP expression is correlated with survival prognosis, MMR mutation, DNA methylation, immunological infiltration, ICP, TMB, MSI, and chemotherapeutic treatment response in pan-cancer." (PMID 38326407, 2024). "Our investigation discovered that CRHBP expression levels were much lower in the majority of cancer types compared to normal tissues, but considerable high expression was also detected in the cancer types LAML, LGG, PAAD, and TGCT, which was consistent with previous findings." (PMID 38326407, 2024). "Low CRHBP expression was linked to a bad prognosis in the following cancers: KIRC (p < 0.001), MESO (p = 0.026), PAAD (p = 0.0017), and SARC (p = 0.0019), whereas high CRHBP expression was linked to a poor prognosis in the following cancers: LAML (p = 0.024), UCEC (p = 0.031), and UVM (p = 0.011)." (PMID 38326407, 2024). "NDUFA4L2, CRHBP and PIGU were top genes with monotonic changes of expression across cancer stages that could represent promising targets for therapy." (PMID 31277598, 2019).
CRHBP also shares sentences with these, for which no sentence is quoted: alcoholism (3 papers); Alzheimer disease (3); mental illness (2); stress-related disorder (2); ameloblastoma (1); cardiomyopathy (1); emotional abnormalities (1); endometrial cancer (1); infection (1); liver cancer (1); lung adenocarcinoma (1); lymph node metastasis (1); nicotine dependence (1); Parkinson disease (1); pituitary adenomas (1); preeclampsia (1); prostate carcinoma (1); substance abuse (1); substance dependence (1).